TAF12-DT (TAF12 divergent transcript)
Synonyms: formerly LINC01715
Gene: Long non-coding RNA gene on chromosome 1 (28,643,159 to 28,648,829, forward strand). Ensembl gene ENSG00000229388.
Gene Ontology:
Molecular function: pre-mRNA 5'-splice site binding
Biological process: mRNA 5'-splice site recognition
Cellular component: U11 snRNP